FBLN5 (fibulin 5)
Description:
Essential for elastic fiber formation, is involved in the assembly of continuous elastin (ELN) polymer and promotes the interaction of microfibrils and ELN. Stabilizes and organizes elastic fibers in the skin, lung and vasculature (By similarity). Promotes adhesion of endothelial cells through interaction of integrins and the RGD motif. Vascular ligand for integrin receptors which may play a role in vascular development and remodeling. May act as an adapter that mediates the interaction between FBN1 and ELN.
Synonyms: FIBL-5; Dance; UP50; EVEC; ARMD3; ADCL2; ARCL1A; CMT1H; HNARMD
Tractability: Antibody: UniProt places it where antibodies can reach, with high confidence; its Gene Ontology location is reachable by antibodies, with high confidence; UniProt predicts a signal peptide or a membrane-spanning region.
Gene: Protein-coding gene on chromosome 14 (91,869,410 to 91,948,064, reverse strand). Ensembl gene ENSG00000140092.
Subcellular location: Secreted; Secreted, extracellular space, extracellular matrix
Subcellular location (Human Protein Atlas): Plasma membrane; Predicted to be secreted
Pathways (Reactome):
Extracellular matrix organization: Elastic fibre formation; Molecules associated with elastic fibres
Gene Ontology:
Molecular function: protein binding; protein homodimerization activity; extracellular matrix constituent conferring elasticity; integrin binding; calcium ion binding
Biological process: elastic fiber assembly; secretion; cell-matrix adhesion; protein localization to cell surface; regulation of removal of superoxide radicals; intramembranous bone growth; negative regulation of angiogenesis; negative regulation of transcription by RNA polymerase II; positive regulation of osteoblast proliferation; positive regulation of transcription by RNA polymerase II
Cellular component: extracellular exosome; extracellular matrix; extracellular region; elastic fiber; non-collagenous component of interstitial matrix
Genetic constraint (gnomAD): Loss-of-function variants: 24 observed, 58.19 expected, observed/expected ratio (o/e) 0.41, 90% interval 0.3 to 0.58. The upper end of that interval is the gene's LOEUF score, 0.58, which puts it in group 2 of 6, group 1 being the genes least tolerant of losing a copy. Missense variants: 441 observed, 587.66 expected, observed/expected ratio (o/e) 0.75, 90% interval 0.69 to 0.81. Synonymous variants: 203 observed, 219.87 expected, observed/expected ratio (o/e) 0.92, 90% interval 0.82 to 1.04.
Gene-disease validity (ClinGen):
ClinGen rates the evidence that FBLN5 causes each of these diseases.
demyelinating hereditary motor and sensory neuropathy (autosomal dominant): Moderate.
Homologues: Orthologues: chimpanzee FBLN5 (99% identical), macaque FBLN5 (98% identical), dog FBLN5 (97% identical), pig FBLN5 (97% identical), rabbit FBLN5 (97% identical), guinea pig FBLN5 (95% identical), mouse Fbln5 (94% identical), rat Fbln5 (94% identical), tropical clawed frog fbln5 (74% identical), zebrafish fbln5 (64% identical). Paralogues in human: EFEMP2 (48% identical), EFEMP1 (44% identical), FBLN1 (34% identical), FBLN2 (33% identical), EYS (28% identical), VWDE (20% identical).
Diseases named in the same sentence as FBLN5 in open-access papers:
FBLN5 is named in the same sentence as 139 diseases in open-access papers, as found by Europe PMC text mining. Sharing a sentence is not in itself a finding about the gene and the disease. The quoted sentences say what the papers report.
cutis laxa (16 papers, 2012 to 2026). Cutis laxa (CL) is an inherited or acquired connective tissue disorder characterized by wrinkled, redundant and sagging inelastic skin associated with skeletal and developmental anomalies and, in some cases, with severe systemic involvement. "Genetic variants in FBLN5 and its deregulation lead to various elastinopathies such as, cutis laxa, pelvic organ prolapse (POP), Charcot-Marie-Tooth disease and AMD." (PMID 36794549, 2023). "Variants in FBLN5 cause a Mendelian form of cutis laxa associated with aortic aneurysm, vascular tortuosity and supravalvular aortic stenosis." (PMID 35922433, 2022). "Mutations in Elastin and Fibulin-5 gene have been reported to associate with patients developing cutis laxa." (PMID 35054981, 2022). "In recessive cutis laxa, reduced extracellular matrix formation was observed under ER stress induced by mutation of fibulin-5." (PMID 25928708, 2015). "Ten fibulin 5 sequence variants have been associated with AMD and two other fibulin 5 mutations caused autosomal-recessive cutis laxa." (PMID 24558588, 2012). "Mutations in FBLN5 are associated with age-related macular degeneration 3, cutis laxa." (PMID 35754816, 2022). "Indicative of shared systems biology, it is notable that cutis laxa, a rare genetic condition caused by mutations in key structural components of elastic fibers (i.e. elastin, fibulin-4, and fibulin-5), manifests with excess inelastic skin and pulmonary emphysema." (PMID 31234847, 2019). "Fibulin-5 is mainly found in elastic fiber-enriched tissues including aorta, lung, uterus, and skin, and its mutations are associated with an autosomal recessive form of a rare congenital skin anomaly called cutis laxa and age-related macular degeneration development." (PMID 30227601, 2018). "Murine models, especially fibulin-5 knockout mice, recapitulate features of cutis laxa, including marked defects in elastic fiber formation." (PMID 41511357, 2026). "Our patient presented with pulmonary fibrosis and recurrent infections, broadening the recognized clinical spectrum of FBLN5-related cutis laxa." (PMID 41300699, 2025). "Missense substitutions leading to improper secretion of FBLN5 and reduced interaction with elastin and fibrillin-1 have been reported in recessive cutis laxa." (PMID 36794549, 2023). "ATS should be differentiated from EFEMP2-related cutis laxa, Loeys-Dietz syndrome, Ehlers-Danlos syndrome, FBLN5-related cutis laxa, LTBP4-related cutis laxa and Occipital horn syndrome." (PMID 34384376, 2021). "Several gene defects, such as those in elastin or fibulin 5, have been found in cutis laxa, suggesting an etiology of defects in elastic fiber synthesis." (PMID 28116317, 2016). "We show that a mouse model of cutis laxa (Fbln5−/−) with disorganized elastic fibers in the large arteries has altered windkessel behavior as early as P7 and investigate the resulting effects on blood pressure and LV function during maturation." (PMID 24760511, 2014). "Further, mutations in FBLN5 have been related to complications such as AMD, cutis laxa and POP." (PMID 36794549, 2023). "FBLN5-related cutis laxa (CL) is a rare disorder that involves elastic fiber-enriched tissues and is characterized by lax skin and variable systemic involvement such as pulmonary emphysema, arterial involvement, inguinal hernias, hollow viscus diverticula and pyloric stenosis." (PMID 33509220, 2021). "However, a detailed mechanism of how Elastin and fibulin-5 are involved in the development of cutis laxa is unknown." (PMID 35054981, 2022).
breast carcinoma (12 papers, 2016 to 2026). "Of note, Fbln2 had significant positive correlations with Fbln1 and Fbln5 in all breast cancer subtypes." (PMID 39110274, 2024). "FBLN5 promotes epithelial-mesenchymal transition (EMT) in breast cancer cells and mediates Nogo-B-stimulated EMT in cervical cancer cells." (PMID 37644092, 2023). "There is increasing evidence that FBLN5 has prognostic potential as a tumor suppressor in a variety of cancers, such as ovarian cancer, breast cancer, and hepatocellular carcinoma." (PMID 35543375, 2022). "FBLN5 reduced the invasion, mammospheres formation, and proliferation capacity of cancer cells via silencing β-catenin phosphorylation in breast cancer and NSCLC, acting as a cancer suppressor gene." (PMID 36306007, 2022). "It has been reported that FBLN5 was significantly down-regulated in ovarian cancer, breast cancer, and lung cancer, and FBLN5 over-expression inhibited cells proliferation and metastasis." (PMID 35543375, 2022). "The downregulated expression of FBLN5 in breast cancer suggested that FBLN5 played the role of tumor suppressor gene in breast cancer." (PMID 34475958, 2021). "The results showed that the expression of FBLN5 in breast cancer was lower than that in the adjacent tissues, and the area under the ROC curve was 0.8650, which had better diagnostic efficiency." (PMID 34475958, 2021). "FBLN5 expression was significantly decreased in breast cancer cells and tumor tissues of breast cancer patients." (PMID 34475958, 2021). "Combined with the clinicopathological data, we found that FBLN5 was correlated with clinicopathological parameters in breast cancer tissues." (PMID 34475958, 2021). "We found that miR-370-3p activated the NF-κB signaling pathway by targeting FBLN5 to promote the proliferation, migration, and stemness of breast cancer cells." (PMID 34475958, 2021). "The expression levels of FBLN5 in breast cancer patients were negatively related with tumor diameter and TNM stage." (PMID 34475958, 2021). "Mechanistically, miR-370-3p inhibited FBLN5 expression and activated the NF-κB signaling pathway to promote breast cancer cell proliferation, migration, and stemness." (PMID 34475958, 2021). "We detected the expression levels of FBLN5 in clinical tissue specimens of patients with breast cancer." (PMID 34475958, 2021). "Collectively, our data firstly demonstrated that miR-370-3p acted as an oncogene in the development of breast cancer by inhibiting FBLN5 expression and activating the NF-κB signaling pathway." (PMID 34475958, 2021). "Our research identified that miR-370-3p promoted breast cancer progression by inhibiting FBLN5 expression and activating the NF-κB signaling pathway." (PMID 34475958, 2021). "In breast cancer, FBLN5 initiated EMT and enhanced the process of TGF-β-induced EMT." (PMID 36672502, 2023). "Therefore, we studied the expression level of FBLN5 in clinical breast cancer and breast cancer tissues, as well as its correlations with clinicopathological parameters." (PMID 34475958, 2021). "In our study, we found that the expression of FBLN5 in breast cancer cells and breast cancer tissues was lower than that in breast epithelial cells and normal breast tissues, which confirmed that the expression level of FBLN5 was negatively correlated with miR-370-3p." (PMID 34475958, 2021). "Taken together, these findings suggested that FBLN5 inhibited the development of breast cancer." (PMID 34475958, 2021). "The sensitivity and specificity of the diagnosis were 80% and 95%, respectively, which indicated that FBLN5 could be a potential candidate of tissue detection for breast cancer diagnosis." (PMID 34475958, 2021). "Similarly, FBLN5 over expression inhibited invasion and proliferation capacity of several breast cancer lines including MCF-7, T47D and MDA-MB-23148." (PMID 27941907, 2016).
breast carcinoma (continued). "Interestingly, reduced levels of fibulin-5 in breast cancer have been reported to be required for metastasis formation in the liver and lung by suppressing the activity of MMP9, a protease that remodels the ECM during metastatic niche formation and promotes metastatic outgrowth." (PMID 33836007, 2021). "FBLN5 may serve as a novel molecular marker in tissue detection for breast cancer." (PMID 34475958, 2021). "In this study, BM genes with differential expression and prognostic correlation in breast cancer were selected as promising prognostic biomarkers for breast cancer, including FBLN1, FBLN5, ADAMTS8, LOXL1, SDC1 and PXDNL." (PMID 37056938, 2023). "Based on the TCGA-BRCA dataset, we found that LOXL1, SDC1 and PXDNL were highly expressed in breast cancer while the expressions levels of FBLN1, FBLN5 and ADAMTS8 were lower than those in normal breast samples." (PMID 37056938, 2023). "In addition, FBLN5 initiates EMT and induces elevated matrix metalloenzyme expression activity to promote breast cancer cell metastasis." (PMID 36672502, 2023). "In addition, FBLN5 acted as a target gene that can be regulated by miRNAs, such as miR-552/370/27a-3pp, thereby exerting the function of an anti-oncogene in NSCLC, breast cancer, and ovarian carcinoma." (PMID 36306007, 2022). "In addition, FBLN5 was negatively correlated with tumor diameter and TNM stage of breast cancer, suggesting that low expression of FBLN5 was a predictor of poor prognosis." (PMID 34475958, 2021).
pelvic organ prolapse (12 papers, 2013 to 2024). Abnormal descent of a pelvic organ resulting in the protrusion of the organ beyond its normal anatomical confines. "This study aims to access the frequency of single-nucleotide polymorphism rs12589592 (G>A) of the fibulin-5 gene in a Brazilian population with pelvic organ prolapse." (PMID 39630761, 2024). "Fibulin-5 knockout mice (Fbln-5-/-) are genetically deficient in elastic fiber assembly and develop pelvic organ prolapse as a function of age." (PMID 39331015, 2024). "Distribution of pelvic organ prolapse case genotypes (pelvic organ prolapse) and controls for single-nucleotide polymorphism rs12589592 of the FBLN5 gene." (PMID 39630761, 2024). "Fibulin 5 deficient mice showed various defects in elastic fiber, including loose skin, vascular abnormalities, emphysematous lung, and genital prolapse." (PMID 34200411, 2021). "Our model in which elastase was injected into the vaginal wall tissue revealed that conditional loss of Fbln5 predisposed to pelvic organ prolapse." (PMID 27124299, 2016). "Mice deficient for the fibulin-5 gene (Fbln5−/−) develop pelvic organ prolapse (POP) due to compromised elastic fibers and upregulation of matrix metalloprotease (MMP)-9." (PMID 23437119, 2013). "MOP-Q assessments were used to determine the impact of serial injections of D+Q on the development of pelvic organ prolapse in Fbln-5-/- and WT mice beginning at 4 weeks of age." (PMID 39331015, 2024). "We utilized a mouse model of pelvic organ prolapse, Fibulin-5 knockout (Fbln-5-/-) mice, to assess the ability of dasatinib and quercetin (D+Q) to prevent development of prolapse." (PMID 39331015, 2024). "Studies on Fbln5−/− mice have shown progressive symptoms of genital prolapse, indicating that FBLN5 may play a crucial role in maintaining the stability of the pelvic floor support structure." (PMID 39334862, 2024). "Loss of the elastogenic organizer, fibulin-5 (FBLN5), leads to pelvic organ prolapse in mice." (PMID 31451729, 2019). "Previously, we identified an unknown serine protease increased in tissues from subjects with pelvic organ prolapse and a candidate serine protease that degraded FBLN5 in vitro." (PMID 29581841, 2018). "Aberrant expression or deposition of FBLN5 has been observed in age-related macular degeneration (AMD), abdominal aortic aneurysms and pelvic organ prolapse (POP) and individuals with these disorders have shown susceptibility to PEX." (PMID 36794549, 2023).
lung carcinoma (10 papers, 2015 to 2023). "Fibulin-5-deficient mice primarily exhibited pulmonary phenotypes such as lung emphysemas, a risk factor of lung cancer." (PMID 25909283, 2015). "The Cancer Genome Atlas (TCGA) datasets show a strong association between loss of fibulin-5 expression and poor outcomes of lung cancer patients, and also activation of the Wnt target genes MMP-7 and c-Myc." (PMID 25909283, 2015). "Loss of fibulin-5 expression is associated with poor survival of lung cancer patients and disease progression." (PMID 25909283, 2015). "In this study, we found that loss of fibulin-5 expression in lung cancer is strongly associated with accumulation of β-catenin and activation of MMP-7 and c-Myc." (PMID 25909283, 2015). "To understand how fibulin-5 suppresses lung cancer progression, we compared the expression of fibulin-5 with other genes implicated in lung cancer progression." (PMID 25909283, 2015). "For example, the protein Fibulin-5 (Uniport id: Q9UBX5) is a product of gene FBLN5, which was reported to suppress lung cancer invasion by inhibiting matrix metalloproteinase-7 expression." (PMID 36930671, 2023). "FBLN5 is downregulated in a majority of cancer types, such as liver cancer and lung cancer, displaying cancer-suppressing effects." (PMID 37644092, 2023). "Another report demonstrated that FBLN5 impedes Wnt/β-catenin signaling by inhibiting ERK activation of GSK3β in lung cancer." (PMID 35543375, 2022). "Given previous studies shown that FBLN5 was involved in lung cancer development via the ERK pathway." (PMID 35543375, 2022). "In lung cancer, overexpression of FBLN5 suppressed cell invasion and metastasis through the ERK pathway." (PMID 35543375, 2022). "FBLN5 was discovered to be a suppressor of lung cancer invasion and metastasis via inhibiting MMP-7." (PMID 34976811, 2021). "For example, previous study reported that epigenetically silenced fibulin 5 promotes invasion and metastasis in lung cancer." (PMID 30279964, 2018). "To further investigate its role in lung cancer, we analyzed the expression of fibulin-5 in large datasets from The Cancer Genome Atlas (TCGA) databases." (PMID 25909283, 2015). "Knockdown of fibulin-5 by siRNA in H1752 lung cancer cells, which express endogenous fibulin-5, was sufficient to induce the expression of nuclear β-catenin, and also promote cell invasion." (PMID 25909283, 2015). "Together, our results suggest that fibulin-5 functions as a metastasis suppressor in lung cancer by modulating tumor microenvironment to suppress Wnt/β-catenin signaling." (PMID 25909283, 2015). "Our results indicate that fibulin-5 functions as a metastasis suppressor in lung cancer by inhibiting Wnt/β-catenin signaling, and provide new insights on lung cancer invasion and metastasis." (PMID 25909283, 2015). "Fibulin-5 is frequently downregulated in more than 50% of lung cancer at least in part due to promoter hypermethylation." (PMID 25909283, 2015). "Fibulin-5 and fibulin-3 suppress lung cancer invasion and metastasis by inhibiting the expression of matrix metalloproteinase 7 (MMP-7), which promotes tumor metastasis by degrading the basement membrane that serves as a barrier to surrounding tissues." (PMID 25909283, 2015). "The prominent role of fibulin-5 in lung cancer is in line with its function in pulmonary physiology and pathology." (PMID 25909283, 2015). "Collectively, our results demonstrate an important functional role of fibulin-5 in suppressing Wnt/β-catenin signaling and lung cancer invasion." (PMID 25909283, 2015). "It is possible that the effect of fibulin-5 in lung cancer involves integrins other than αvβ3, which will be investigated in our future studies." (PMID 25909283, 2015). "We previously identified fibulin-5, an extracellular matrix protein, as a frequently silenced gene in lung cancer and a suppressor of cell invasion." (PMID 25909283, 2015).